IL13 (interleukin 13)
Diseases named in the same sentence as IL13 in open-access papers (continued):
Sharing a sentence is not in itself a finding about the gene and the disease.
infection (continued). "For instance, serum and plasma from patients with a mild to moderate infection contained significantly greater levels of MCP-3, IL-1α, TNFβ, IL-4, IL-5, IL-6, IL-8, IL-9, and IL-13 compared to serum and plasma from patients that were critically ill." (PMID 34790978, 2021). "Our results showed an increase in cytokines IL-4 and IL-13 in the BAL of XID mice on the 7th and 19th day of infection." (PMID 34526536, 2021). "Although this was the case, the noticeable decreases in IL-1β, IL-2, IL-4, IL-12, IL-13, RANTES, TNF-α, and GRO-α observed in patients with lethal SARS-CoV-2 infection suggest that lethal infection results in an exhausted immune response." (PMID 33472985, 2021). "The replicate cultures were either mock-treated, IL-13 treated (5 days), or infected with HRV-A or HRV-C (24 h post-infection)." (PMID 33046696, 2020). "Several human VL studies have demonstrated elevated serum levels of IL-4, IL-6, IL-10, IL-12, IL-13, IFN-g, and TNF-a in active disease compared to asymptomatic infection." (PMID 32321156, 2020). "In the early stage of infection, IL-6, G-CSF, and IL-13 levels were high in the A/Zhejiang/DTID-ZJU01/2013(H7N9) and A/Guangdong/GZ8H002/2017(H7N9) infection groups." (PMID 32267217, 2020). "No changes were observed in the levels of the anti-inflammatory cytokines (IL-10 and IL-13) and the pro-inflammatory cytokines TNF-α in brain homogenates of WT and MBL-null mice after infection with HSV-1." (PMID 31869396, 2019). "Concordant with the murine macrophage data, M(IL-4/IL-13) polarized human MDMs also exhibited a significantly reduced intracellular growth of Mtb HN878 upon miR-143 and miR-365 knockdown at 24 h post-infection." (PMID 30941122, 2019). "Here, we show that infection with helminths in the intestine also induces an ILC2-driven, IL-13–dependent goblet cell hyperplasia and increased production of mucins (Muc5b and Muc5ac) at distal sites, including the lungs and other mucosal barrier sites." (PMID 31582416, 2019). "When effector lymphocytes traffic to the inflammatory site, they secrete a large amount of pro-inflammatory cytokines such as IL-4, IL-13, IFN-γ, which induce an intense inflammatory response to clear the pathogen infection." (PMID 31921198, 2019). "Among the cytokines analyzed for this study, IL-4, IL-5, IL-10, IL-13, and TGF-b participate in the resolution of infection-related pulmonary inflammation." (PMID 31271354, 2019). "A recent one-year longitudinal study of confirmed MAYV-infected individuals in Peru found that infection elicited robust anti-viral immune responses including strong neutralizing antibody responses and secretion of pro-inflammatory immune cytokines including IL-13, IL-7, and VEGF." (PMID 30730897, 2019). "C57BL/6 mice that receive a single high dose infection develop resistance, dependent on CD4+ Th2 cells and IL-13 production." (PMID 31730667, 2019). "As our findings suggested that IL-4/IL-13 treatment enhanced rVSV/EBOV GP infection in an EBOV GP-dependent manner, we evaluated the earliest steps in infection: binding and entry." (PMID 31825972, 2019). "A substantial decrease in IL-6, IL-9, IL-12p40/p70, IL-13, IL-17, IFN-γ, CCL5, SCF, TNF-α, TPO, and vascular endothelial growth factor (VEGF) was observed across days 4 through 7 of NTHi infection." (PMID 31548315, 2019). "Administration of IL-4/IL-13 to macrophages significantly enhanced EBOV GP-dependent viral particle binding and internalization with increases in overall infection." (PMID 31825972, 2019). "Functional studies in mice show that IL-13+ ST2+ ILC2 are most prominent between 6 and 10 days post infection." (PMID 30174671, 2018). "In both infections, we observed an increase in IFN‐γ, TNF‐α, IL‐6, IL‐8, IL‐10, IL‐13, MIP1β, and G‐CSF levels." (PMID 29314720, 2018). "Mice with IRF4 deficient CD11c+ cells had less secretion of IL-4, IL-15 and IL-13 after immunization with OVA and papain as well as during infection with the nematode Nippostrongylus brasiliensis." (PMID 29343807, 2018).
infection (continued). "At week 5, the infection of the mouse heart was determined, showing that CVB3 significantly increased heart inflammation, which was significantly attenuated by IL-13 injection, shown by quantification, and by representative images." (PMID 29245918, 2017). "Analysis of cytokines production by spleen and MLN cells in mice model have shown the production of IL-4, IL-10, IL-13, IL-17, IL-22, TNF-α, and IFN-γ after infection with both WB and GS strains." (PMID 28979269, 2017). "There was a significant increase at day 7 relative to day 5 post-infection in abundance of interleukins (IL) including IL1B, IL2, IL4, IL5, IL6, IL10 and IL13." (PMID 27311020, 2016). "Under these conditions, primary infections resulted in the development of a local Th1 phenotype as shown by upregulation of IFN-γ and low levels of IL-4 and IL-13." (PMID 27658962, 2016). "However, some general points can be made: Th2-associated cytokine levels were higher overall, as might be expected given the nature of the infection; IL-3, IL-4, IL-5, IL-10 and IL-13, were all elevated in popLN cells from infected limbs, particularly so when re-stimulated with Brugia antigen." (PMID 27992545, 2016). "Restricting Il4 deficiency to ILC2s in vivo revealed an important role of ILC2s for the differentiation of IL-13+ and IL-5+ TH2 cells following infection with H. polygyrus." (PMID 26883724, 2016). "In contrast, 24 weeks of infection induced new changes in other inflammatory molecules with reduced KC, MCSF, enhancing GM-CSF, IFNγ, IL-1β, IL-13, IL-4, IL-13, lymphotactin, RANTES, and also an increase in select inflammatory molecules." (PMID 26619277, 2015). "The most dramatic effects of infection with ECTV-IFN-γbpΔ in the GKO mouse strains were evident in STAT-6−/− and IL-13−/− mice." (PMID 25751266, 2015). "Kinetics of production of individual cytokines varied: TNF-α was secreted early after infection while other cytokines (IL-10, IL-13, IFN-γ) became detectable 24 to 48 hours post-infection." (PMID 26024228, 2015). "In humans, type II NKT cells that produced large amounts of IFN-γ, but little IL-13 or IL-4, accumulated in the liver during hepatitis C (HCV) infection, but their role during infection remains to be determined." (PMID 26284062, 2015). "The total numbers of DX5+ NK cells were not altered significantly in GKO strains compared with WT mice following infection with ECTV-WT, with the exception of the IL-13−/−/IL-4Rα−/− mice in which the numbers were about 5-fold lower." (PMID 25751266, 2015). "Consistent with results of the cytokine analysis, IL-13 and TGF-β1 werealso shown to be markedly reduced in ICOSL KO mice compared to the WT controls at 12 weeks post-infection (P<0.001)." (PMID 25590646, 2015). "Compared with uninfected mice, infected wild-type mice showed higher levels of IL-4, IL-10 and IL-13, with similar levels of α-smooth muscle actin, galectin-3, TGF-β1, IL-17, IFN-γ, and lower IL-12 levels at 90 days post-infection." (PMID 25032961, 2014). "We also found that stimulated peripheral blood mononuclear cells (PBMCs) produced significantly increased levels of a number of cytokines at the convalescent versus acute phase of infection, including IFN-γ, MIP-1β, sCD40L, TNF-β, IL-13, and IL-9." (PMID 24615129, 2014). "We found no activation or even reduction in base-line expression for multiple molecules (IL-7, IL-4, IL-13, GATA3, ROR-γt, and CXCL12) at 2, 6 and 10 days post-infection." (PMID 25254971, 2014). "Taken together, some proportion of the hepatic CD4+ T cells in the liver during the transition phase of the infection indeed acquired the capacity for producing IFN-γ, IL-13, and IL-4 simultaneously (“triple positive cells”)." (PMID 24358216, 2013). "A multiplexed bead assay was used to measure plasma levels of IL-5, IL-10, IL-12, IL-13, IFN-γ and TNF in BALB/c mice immunized against P. berghei K173 by repeated infection and drug cure before the first pregnancy." (PMID 24180253, 2013).
infection (continued). "This was accompanied by abundant CD4+ and CD8+ T cells exhibiting an activated phenotype and induction of interleukin 13 (IL-13)- and GATA3-expressing Th2-type CD4+ T cells that remained present in the airways even 14 days after infection." (PMID 23926350, 2013). "Wild type mice resist infection with N. brasiliensis and develop polarized TH2 responses with high IL-4/IL-13 and low IFN-γ production." (PMID 23284939, 2012). "In addition, female IL-4 KO mice on a BALB/c background which, unlike males, can clear a high dose infection of T. muris (although delayed compared to wild-type mice) become susceptible after IL-13 neutralization, indicating a dominant role for IL-13 in immunity against T. muris." (PMID 23053395, 2012). "Prior to infection protectively vaccinated mice exhibit augmented CD4 and CD8 IFNγ and memory responses as well as decreased IL-10 and IL-13 responses." (PMID 21695103, 2011). "We show that infection in AAD significantly reduced eosinophilic inflammation, OVA-induced IL-5, IL-13 and IFN-γ responses and AHR; however, infection increased airway neutrophil influx in response to OVA challenge." (PMID 21998577, 2011). "Overall, hypersecretion of glycoproteins into the extrinsic barrier (mediated by IL-13) via the gamma amino-butyric acid-α3 receptor (GABA-α3), was observed during acute infection." (PMID 21155842, 2011). "Infection during (d0 NTHi+OVA) or after (d10 NTHi+OVA) sensitization resulted in significant reductions in OVA-induced IL-5, IL-13 and IFN-γ release from MLN T cells, compared to uninfected, allergic (OVA) controls." (PMID 21998577, 2011). "On a cellular level, Cmu infection of bone marrow-derived dendritic cells (BMDC) modulates the cytokine profile from both DCs and T cells to produce increased IL-13 in vitro." (PMID 21573182, 2011). "As the most abundant cell population in the skin after 4x infections wereSiglecF+ eosinophils, and R2 eosinophils sorted from total DECexpressed abundant mRNA for IL-4 and IL-13, we propose that eosinophils may be theprimary source of the copious IL-4 and IL-13 released by 4x skin biopsies." (PMID 21445234, 2011). "We found that both infection regimes resulted in Th2-type immune response, characterised by IL4 and IL13 produced by S. ratti stimulated mesenteric lymph node cells, anti-S." (PMID 18575588, 2008). "Infection levels by Schistosoma are controlled by a major locus on chromosome 5q31-q33 containing the IL4, IL5 and IL13 genes related to the Th2 immune response." (PMID 19471606, 2008). "This shows that for both infection regimes there were convex relationships with time p.i. for the concentration of IL4 and IL13 produced by MLN cells stimulated with parasite antigen and for the concentration of anti-S." (PMID 18575588, 2008). "For example, at 9 wk post-infection, the percentage of CD4+ T cells that were IL-13 positive was 17.1% and 11.8% in WT and CAT2−/− mice, respectively, while only 0.19% and 0.2% were IL-17 positive." (PMID 18369473, 2008). "We observed some small quantitative immunological differences between different infection regimes, in which the concentration of IL4, IL13, anti-S." (PMID 18575588, 2008). "While wild-type mice generally did not succumb to infection, they maintained persistent pulmonary load out to at least 5 months, which was lost in Il4/Il13−/− mice." (PMID 40568097, 2025). "During secondary infection, CD4+ T cell-dependent Th2-type memory is required for host protection against the parasite, which includes the induction and recruitment of alternatively activated macrophage (AAMacs) by IL-4/IL-13." (PMID 40501701, 2025). "Expression of this cluster peaked at 2d post infection and showed statistically similar expression patterns with or without IL-13 stimulation, suggesting that IL-13 does not affect expression of interferons and the upstream elements of the ISG cascade." (PMID 41427379, 2025).
infection (continued). "In our model, neutralisation of IL-13 during early CR infection did not significantly alter clinical disease parameters but resulted in reduced colonic levels of IL-10 and IL-22." (PMID 40591723, 2025). "It is therefore possible that IL-4 plays a decisive role in the initial stages of lesion development, while IL-13 promotes a chronic, nonhealing form of the infection." (PMID 39963187, 2025). "Secreted IL-13 was detectable in the pediatric group during the acute phase of infection, and IL-22, but not IL-13, levels correlated with age in the pediatric group (IL-22 P = 0.002 and <0.0001)." (PMID 40906527, 2025). "To analyze further functional states of THP-1 cells, which might influence the sensitivity for TcpC during an infection with CFT073, we polarized THP-1 cells to M1 and M2 macrophages using PMA/IFNγ/LPS or PMA/IL-4/IL-13, respectively." (PMID 41310197, 2025). "The inflammatory cytokines TNFα, IL-4, IL-6, IL-13, IL-10, IL-12 (P40), and IL-12 (P70) along with chemokines including CCL2, CCL3, and CCL5, were significantly elevated in the plasma of c-Flip+/–mice on day 2 post-infection compared that of WT mice." (PMID 39038037, 2024). "As expected, IL‐13 levels in the lung exhibited a gene‐dose effect with an increase upon infection in WT mice, which was reduced in HET mice and absent in the KO mice." (PMID 39606183, 2024). "Conversely, SmLE infection resulted in elevated levels of IL-2, IL-4, IL-5 and IL-6 and a decrease in IL-13 in C57BL/6 but not in BALB/c mice." (PMID 38711063, 2024). "We previously observed significant increases in ileal TNF-α and IL-13 as well as profound differences by network analyses of other host immune factors over time during P. y. yoelii 17XNL infection in basophil-depleted relative to nondepleted mice." (PMID 38780542, 2024). "IL-5, IL-13, and 25(OH)D levels were negative predictors of infection in stunted children, meaning that a child with lower IL-5, IL-13, and 25(OH)D levels would be more vulnerable to becoming ill if infected by STHs." (PMID 38393122, 2024). "In contrast with IL-4, IL-5, and IL-13, mRNA expression of IL-1β and TNF-α, both considered type 1 cytokines, decreased after infection with RV2, suggesting that RV infection on day 6 of life skewed the response to subsequent heterologous RV infection toward a type 2 phenotype." (PMID 38061015, 2024). "of ruminants can provoke serious health problems and because the infected host may modulate the infection through the activity of IL4, IL5, IL13, and the FCεR1A receptor genes." (PMID 39057830, 2024). "Overexpression of IL-13 in C57BL/6 mice, which are typically resistant to Leishmania major infection, renders them susceptible to infection, irrespective of IL-4 expression." (PMID 37908348, 2023). "Neither infection with Mtb nor treatment with hSAA-1 induced the expression of Th2 cytokines in MDMs, namely IL-4 and IL-13, which polarize macrophages to an M2 activation status." (PMID 37781389, 2023). "This notion is also in agreement with our observation that infection with C. perfringens increased expression of IL-18 and IL-13 and not IL-12p40." (PMID 38164397, 2023). "The absence of IL-13 in mice infected with L. amazonensis significantly reduced paw swelling at the site of infection." (PMID 37908348, 2023). "Treatment of adiponectin during infection did not affect IFNγ and IL-17 cytokine production but enhanced IL-13 secretion levels in small intestinal tissues." (PMID 37635188, 2023). "In contrast, greater production of IL-4, IL-13, IL-9, and IL-2 was observed following drug treatment irrespective of infection status, consistent with the observation of increased Th2 populations at the PDTB stage." (PMID 37898618, 2023).
infection (continued). "The shift from M1 to M2 during the infection course was correlated with the secretion of Th1 cytokines (IFN-γ and TNF-α), changing to Th2 cytokines (IL-10 and IL-13), further indicating that M1 is related to the pro-inflammatory response and M2 to the Th2/regulatory response." (PMID 36668953, 2023). "This contrasts with our data in the murine model that have demonstrated that Mo-MDSCs and PMN-MDSCs infiltrated the site of infection of L. sigmodontis-infected BALB/c mice and that only Mo-MDSCs exhibited suppressive capacities on the production of IL-13 and IFN-γ by CD4+ T cells." (PMID 37242335, 2023). "At week 4 post infection, CD4+ T-cells showed a mixed response to S. mansoni AWA by secreting cytokines which encompassed Th1 (IFNγ, TNFα, IL-2 & IL-1β), Th2 (IL-4, IL-5, IL-13) and regulatory responses (IL-10) as well as the regulatory T cell transcription factor Foxp3." (PMID 37837930, 2023). "Unlike in control mice there was no significant increase in IL-4 or IL-13 serum levels in CD1d-/- mice detectable at day 5 pi suggesting that iNKT cells are major producers of these cytokines during early infection." (PMID 36159876, 2022). "At day 5 to 6 post infection, we observed an upregulation of IL-4, but not of IL-5, IL-10 or IL-13 mRNA." (PMID 35894051, 2022). "However, to ensure complete removal of mucus, NT and IL-13–treated cells were thoroughly washed with phosphate-buffered saline (PBS; 3 × 1 h) prior to infection and compared with unwashed cells." (PMID 35353667, 2022). "In IL-13–treated HAE cells, mucus may further protect the cells against infection, which was tested by comparing bolus versus drop inoculations." (PMID 35353667, 2022). "Furthermore, in macrophages, lincRNA-MIR99AHG is translocated to the nucleus and interacts with high affinity to hnRNPA2/B1 following IL-4/IL-13 stimulation and Mtb HN878 infection." (PMID 35895506, 2022). "Altogether, these data show that MIR99AHG expression varies according to the macrophage polarization state; in IL-4/IL-13 polarized macrophages MIR99AHG expression was induced, while the expression of MIR99AHG was downregulated following Mtb HN878 infection and in active TB patients." (PMID 35895506, 2022). "Knockdown of MIR99AHG by ASOs significantly reduced the intracellular Mtb growth in IL-4/IL-13 stimulated macrophages at 72 h post Mtb HN878 infection but did not change the phagocytic ability of macrophages to uptake Mtb at 4 h postinfection." (PMID 35895506, 2022). "Serum cytokine levels revealed long-term maintenance of altered profiles even in the case of treatment, with infection increasing IL-2, IL-13, GM-CSF, IL-5, among other cytokines, but these were not markedly altered following treatment (Supplement 1B)." (PMID 35833137, 2022). "In contrast, the downregulation of RANTES/CCL5, MIP-1α/CCL3, and MIP-1β/CCL4 from the early to middle phase of the infection as well as the downregulation of MIG/CXCL9, IP-10/CXCL10, and IL-13 in the middle phase of the infection were observed in aged BALB/c mice." (PMID 35264719, 2022). "Finally, the ileum cytokines IL-2, IL-12p70, IL-13, IL-17, GM-CSF, IFN-γ, TNF-α, and IL-33 remained unchanged relative to baseline over the course of infection in both genotypes." (PMID 35985797, 2022). "it was demonstrated that during RSV responses, the IL-12 production was negatively related to IL-13 production, that IL-12/IL-13 axis was central to elicit an effective or innefective immune response to RSV infection and central to dictate the infection severity." (PMID 35686128, 2022). "In the cortex of adult mice exposed to JWH-018 as adolescents, we found an increasing trend in IL4 levels and an increase in RANTES, a chemotactic cytokine that directs leukocytes to sites of inflammation and infection, along with a decrease in IL2 and IL13 expression compared to vehicle mice." (PMID 35943523, 2022).